EIF4E2 (eukaryotic translation initiation factor 4E family member 2)
Diseases named in the same sentence as EIF4E2 in open-access papers:
EIF4E2 is named in the same sentence as 26 diseases in open-access papers, as found by Europe PMC text mining. Sharing a sentence is not in itself a finding about the gene and the disease. The quoted sentences say what the papers report.
glioblastoma (5 papers, 2013 to 2025). The most malignant astrocytic tumor (WHO grade IV). "Similarly, HIF2α has been shown to regulate GPx1 to ensure resistance to oxidative stress and radiation, while contributing to glioblastoma progression via various mechanisms such as the DDX28-mediated regulation of eIF4E2-driven translation." (PMID 38893207, 2024).
breast carcinoma (4 papers, 2014 to 2025). "Here, we found that translation initiation factor eIF4E1, but not eIF4E2, eIF4G1, eIF1A, eIF2α, or eIF5, is significantly enhanced in breast CSCs in comparison to non-CSC breast cancer cells." (PMID 25115391, 2014). "We found that eIF4E1 (also named eIF4E), but not eIF4E2, eIF4G1, eIF1A, eIF2α, or eIF5, is significantly increased in BCSCs, in comparison to SKBR-3, MCF-7 and MDA-MB-231 breast cancer cells and non-BCSCs of HMLER (CD44high/CD24low)SA cells." (PMID 25115391, 2014).
glioma (2 papers, 2019 to 2023). A benign or malignant brain and spinal cord tumor that arises from glial cells (astrocytes, oligodendrocytes, ependymal cells). "The respective expression levels of NCBP1 and EIF4E2 proteins were lower and remarkably elevated in glioma tissues compared to the relatively healthy brain tissues, as per a Western blot analysis of 10 LGG tissues and 10 healthy brain tissues." (PMID 36998056, 2023). "Analysis of data available on REMBRANDT and TCGA databases revealed that EIF4E1 and EIF4E3 mRNA levels are downregulated whereas EIF4E2 is overexpressed in gliomas." (PMID 31795417, 2019). "Immunohistochemistry analysis showed that EIF4E, EIF4E3, and NCBP2 were increased in lower-grade glioma tissues, while lower-grade glioma did not cause a significant difference in EIF4E2 and NCBP1 proteins." (PMID 36998056, 2023). "Thus, decreased expression of eIF4E1 and eIF4E3 together with increased eIF4E2 expression suggests a global repression of cap-dependent translation in gliomas." (PMID 31795417, 2019). "Western blot analysis showed that the protein expression levels of EIF4E2 and NCBP1 were significantly elevated in glioma tissues compared to matched healthy brain tissues." (PMID 36998056, 2023). "Inhibition of eIF4E2 under hypoxic condition decreases wound healing, cell migration, and sphere formation in the U87MG human glioma cell line." (PMID 31795417, 2019). "In contrast, immunohistochemical analysis of 10 refractory epilepsy tissues and 10 lower-grade gliomas (WHO grade II-III) tissues showed that lower-grade gliomas did not significantly increase in EIF4E2 and NCBP1 protein expression, while EIF4E, EIF4E3, and NCBP2 were increased." (PMID 36998056, 2023).
lung carcinoma (2 papers, 2025 to 2026). "In gastric cancer, METTL3 interacts with poly(A) binding protein cytoplasmic 1 (PABPC1) and stabilizes its association with the cap-binding complex eukaryotic translation initiation factor 4F (eIF4F), whereas METTL16 directly interacts with the translation repressor eIF4E2 in lung cancer." (PMID 41459114, 2026). "In lung cancer, METTL16 has been shown to interact with eIF4E2, a translation repressor, preventing its interaction with the mRNA 5′ cap structure." (PMID 41459114, 2026). "Recent studies have unveiled a novel, m6A-independent role of METTL16 that promotes translation and tumorigenesis by interacting with eIF4E2 in lung cancer independent of m6A catalytic activity." (PMID 40734692, 2025).
viral infection (2 papers, 2020 to 2021). "Further analysis demonstrated that the wider resistance spectrum by pot1 was comparable to that by an eIF4E1 and eIF4E2 double mutant, suggesting that pot1 lacks the function to support viral infection but can compete with eIF4E2 or inhibit its interaction with viruses." (PMID 34454519, 2021).
hepatocellular carcinoma (1 paper, 2023). A malignant tumor that arises from hepatocytes. "Next, we orthogonally validated the observed protective phenotypes of inactivated NFKBIA, EIF4E2, and EIF4H by generating knockout lines from Huh7.5.1 (hepatocellular carcinoma) cells ectopically expressing ACE2 and TMPRSS2." (PMID 37803001, 2023).
ischemic stroke (1 paper, 2025). A stroke disorder caused by obstruction of blood flow to the brain, due to thrombotic (local blood clot formation) or embolic (due to a blood clot or other material traveling from another site) event. "In our previous research on ischemic stroke, we discovered that eIF4E2 ISGylation may play a role in its pathological processes." (PMID 41022323, 2025). "Thus, eIF4E2's ISGylation could potentially modulate GSK3β kinase activity and may regulate the eIF4E2-GSK3β pathway, playing a critical role in ischemic stroke." (PMID 41022323, 2025). "Using these methods, we found that eIF4E2 ISGylation provides significant cytoprotection in neurons and microglial cells after OGD/reoxygenation (OGD/R) stress, highlighting the therapeutic potential of targeting protein ISGylation in modulating intracellular signaling in ischemic stroke." (PMID 41022323, 2025).
liver fibrosis (1 paper, 2022). "Blocking eIF4E2-GSK3β interaction promoted liver senescence under hypoxia, thus leading to liver fibrosis, eventually accelerating N, N-diethylnitrosamine (DEN)-induced tumorigenesis." (PMID 35568694, 2022).
lymphoma (1 paper, 2020). A malignant (clonal) proliferation of B- lymphocytes or T- lymphocytes which involves the lymph nodes, bone marrow and/or extranodal sites. "The overproduction of EIF4E2 AAb in lymphoma patients may inhibit the downstream translation of oncogenic proteins like VEGF, MYC, cyclins, and STAT1." (PMID 32483460, 2020). "SIX2 and EIF4E2 AAbs were further validated in independent cohorts of 17 NSCLC and 43 lymphoma patients, respectively, using ELISA." (PMID 32483460, 2020).
metastatic cancer (1 paper, 2022). A carcinoma which has spread from the original site of growth to another anatomic site. "Among a variety of solid carcinomas, EIF4E2 is considered to be a valuable biomarker for distinguishing metastatic cancer from primary tumors." (PMID 36118897, 2022).
Stroke (1 paper, 2025). Sudden impairment of blood flow to a part of the brain due to occlusion or rupture of an artery to the brain. "The application of eIF4E2-targeting NITAC may help elucidate its function in stroke." (PMID 41022323, 2025). "We used a murine middle cerebral artery occlusion/reperfusion (MCAO/R) model to induce stroke, and post-MCAO/R analysis revealed significantly elevated eIF4E2 ISGylation in the ipsilateral cortex compared to sham controls, while total eIF4E2 expression remained unchanged." (PMID 41022323, 2025).
cancer (13 papers, 2015 to 2025). A tumor composed of atypical neoplastic, often pleomorphic cells that invade other tissues. "In 2017, CDH22 mRNA was identified as a hypoxic eIF4E2 target that encodes cadherin-22, a cell-cell adhesion molecule providing cancer cells with collective migratory and invasive properties specifically in hypoxia." (PMID 29317983, 2017). "Notably, EN2 interacted with the eukaryotic initiation factor eIF-4E2, which is associated with translation under hypoxic conditions and is exploited in cancer." (PMID 37686522, 2023). "Under this condition, cells depleted for eIF4E2 from different types of cancer, including the GB line U-87 MG, showed impaired proliferation and increased apoptosis." (PMID 36994107, 2023). "It was demonstrated that the phenotypic expressions of cancer genomes need to be translated through the hypoxia protein synthesis mechanism guided by eIF4E2." (PMID 36118897, 2022). "Cadherin-22 is a cell-surface molecule target of EIF4E2 and it is involved in cell migration, invasion and adhesion during cancer development." (PMID 33175867, 2020). "While an eIF4E2 targeting drug has immense potential as a cancer therapy, there has been difficulty finding a compound that can distinctively target eIF4E2 over eIF4E." (PMID 30925920, 2019). "By inhibiting eIF4E2, and consequently inhibiting hypoxic protein synthesis, cancer cells can be distinctively targeted from healthy cells by inhibiting the hypoxic protein synthesis pathway." (PMID 30925920, 2019). "Cancer cells exploit the eIF4E2-mediated protein synthesis to sustain hypoxic conditions and consequently grow to significant sizes." (PMID 28210261, 2017). "In 2014, several cancer cell lines stably depleted for eIF4E2 (U87MG glioblastoma, 786-O renal cell carcinoma, and HCT116 colorectal carcinoma) displayed impaired proliferation and increased apoptosis only in hypoxia." (PMID 29317983, 2017). "Current evidence demonstrates that suppression of eIF4E2 via lentiviral-delivered shRNAs is effective at stalling or reversing tumor growth in mouse xenografts of several different cancer cell lines." (PMID 29317983, 2017). "The inconsistency in human eIF4E2 nomenclature has likely played a role in delaying the dissemination of its connection to cancer." (PMID 29317983, 2017). "Dozens of eIF4E2 mRNA targets have strong ties to cancer such as a group of receptor tyrosine kinases including EGFR, platelet-derived growth factor receptor-alpha, insulin-like growth factor 1 receptor, and HER-2, which most cancers overexpress at least one." (PMID 29317983, 2017). "Cancer cells displayed a shifted window of dual eIF4E and eIF4E2 usage (3–12% O2) suggesting that eIF4E2 is activated and eIF4E is sequestered at higher oxygen levels relative to primary cells." (PMID 29317983, 2017). "The phenotypic expression of the cancer genome involved translation by the eIF4E2-directed hypoxic protein synthesis mechanism." (PMID 26275051, 2015). "Evidence suggests that eIF4E2 suppression significantly slows or even reverses cancer growth." (PMID 30925920, 2019). "Another method of targeting hypoxic cancer cells is by inhibiting eIF4E2 activity." (PMID 30925920, 2019). "Therefore, there is still a need to identify a cancer therapy that specifically targets eIF4E2 to inhibit protein synthesis in hypoxic cancer cells." (PMID 30925920, 2019). "Therefore, while eIF4E2 is involved in tumor growth and several cancer cell hallmarks in vitro, future studies should aim to more tightly link eIF4E2 to high-risk, metastatic cancer disease." (PMID 29317983, 2017). "Indeed, studies have shown that overexpressing eIF4E selectively disables hypoxic tumor cells and eIF4E2 mRNA targets are enriched in cancer-driving genes." (PMID 29317983, 2017). "Several classic and modern cancer therapeutics target essential processes such as cell proliferation and protein synthesis, but eIF4E2 initially emerged as a potential drug target that could be more selective to cancer cells." (PMID 29317983, 2017).
cancer (continued). "Thus, proteins synthesized via eIF4E2 offer the possibility of being prognostic markers of hypoxia in cancer patients and eIF4E2, an attractive therapeutic target to disable the adaptation of cells to the hypoxic tumor microenvironment." (PMID 29317983, 2017). "This review consolidates studies using several different eIF4E2 aliases to highlight that it is conserved across eukaryotes and could have a role in advanced cancer stage in humans." (PMID 29317983, 2017). "However, evidence suggests eIF4E2 as a significant contributor for cancer cells to display various cancer hallmarks, for tumor growth, and as a possible predictor of metastasis and poor outcome." (PMID 29317983, 2017). "Cadherin-22, a cell-cell adhesion molecule, is upregulated by promoter eIF4E2-mediated mTORC1-independent translational control during hypoxia; the novel function of cadherin-22 acts as a hypoxia-specific cell surface molecule and is involved in cancer cell migration, invasion, and adhesion." (PMID 36979474, 2023). "In addition, m7G genes such as EIF4E2, DCPS, WDR4, and METTL1 were highly correlated with RARA-AS1 in multiple types of cancer (greater than 10 types)." (PMID 37833349, 2023). "The connection to cancer progression was not surprising considering the identity of the eIF4E2 mRNA targets identified through PAR-CLIP." (PMID 29317983, 2017). "It will be a priority that interventions targeting eIF4E2 hit the metastatic and/or progressive phenotype, and not just cancer cells." (PMID 29317983, 2017). "Targeting eIF4E2-driven translation could be more selective to cancer cells, or at least hypoxic tumor cells, rather than healthy cells because chronic hypoxia is associated with disease." (PMID 29317983, 2017).
tumor (13 papers, 2014 to 2026). "Development of therapeutics targeting eIF4E2 is in their infancy as this cap-binding protein has only recently been linked to tumor growth and its mechanisms of initiation and regulation are only beginning to be elucidated." (PMID 29317983, 2017). "This review will focus on a noncanonical cap-dependent translation initiation mechanism that utilizes the eIF4E homolog eIF4E2, a hypoxia-activated cap-binding protein that is implicated in hypoxic cancer cell migration, invasion, and tumor growth in mouse xenografts." (PMID 29317983, 2017). "Correspondingly, there were some genes that were part of the CAP formation genes, such as NCBP3, NUDT4, CYFIP2, SNUPN, and EIF4E2, which were weakly expressed in most tumor tissues and highly expressed in normal tissues." (PMID 36226166, 2022). "This literature review will focus on an alternative cap-dependent translation mechanism that utilizes the eIF4E homolog eIF4E2, a cap-binding protein that is part of a metastatic gene signature and required for tumor growth in mouse xenografts." (PMID 29317983, 2017). "Perhaps during gradual tumor hypoxification, there is selective pressure on hypoxic cells to repress eIF4E-dependent translation early and activate eIF4E2 early." (PMID 29317983, 2017). "Targeting eIF4E2 relative to eIF4E has the potential to be more selective for malignant cells (hypoxic tumor cells) subsequently leading to lower toxicity." (PMID 29317983, 2017). "Moreover, transcriptomic and Q-PCR analyses showed increased expression of Stat1, Zbp1, Parp14, Irf1, and Tifa along with decreased Eif4e2 in the SOR treatment group compared to the tumor control group." (PMID 42194025, 2026). "This combination therapy specifically activates the cGAS-STING signaling pathway and stabilizes the mRNA expression of the chemokine CXCL10 through an EIF4E2-dependent mechanism, thereby promoting T-cell infiltration into the tumor microenvironment and enhancing anti-tumor immune responses." (PMID 41367875, 2025). "In addition to NUDT16 being a protective factor, the other three genes (WDR4, EIF4E2, and SNUPN) are risk factors that accelerate tumor progression." (PMID 38987843, 2024). "Our data suggest that upregulation of three angiogenesis‐associated genes including HIF‐1, EIF4E2 and VEGFA in TNBC could be mediated by circ_0047303 through sponging the tumour‐suppressive miRNAs." (PMID 34791795, 2021). "In 2003, the metastatic potential of multiple tumor types could be predicted by a six-gene signature that contained EIF4E2 (named eIF4EL3 in this study)." (PMID 29317983, 2017). "Furthermore, EIF4E2 is required for tumor progression, such as tumor growth in mouse xenografts." (PMID 36118897, 2022). "Numerous studies have found that m7G regulator hub genes (EIF4E, EIF4E3, EIF4E2, NCBP1, and NCBP2) are crucial in tumor progression and metastasis." (PMID 36998056, 2023). "It was not until the response of the eIF4E2 protein to hypoxia was described at the molecular level in 2012 that studies began emerging examining its role in tumor growth." (PMID 29317983, 2017). "Moreover, our results suggest that circ_0047303 could mediate the upregulation of key angiogenesis‐related genes, including HIF‐1, EIF4E2 and VEGFA in TNBC through sponging the tumour‐suppressive miRNAs." (PMID 34791795, 2021).
infection (5 papers, 2011 to 2023). The state of being infected such as from the introduction of a foreign agent such as serum, vaccine, antigenic substance or organism. "Further investigation to determine which transcripts EIF4E2 binds to in the setting of infection with ribosome profiling will aid our understanding of the underlying mechanism of EIF4E2 utilization by coronaviruses." (PMID 37803001, 2023). "The previous studies indicated that PVY primarily uses eIF4E1, but most PVY strains can alternatively use eIF4E2 to promote infection when eIF4E1 is knocked out or down." (PMID 33362728, 2020). "We further identified the NF-κB inhibitor IκBα (NFKBIA), as well as the translation factors EIF4E2 and EIF4H as strong host dependency factors acting early in infection." (PMID 37803001, 2023). "Our results suggest that PVYO is one of the major PVY strains that can alternatively use eIF4E2, whereas PVYN is one that exclusively uses eIF4E1 to promote infection." (PMID 33362728, 2020). "NFKBIA knockout cells displayed a 31.8% decrease in infection, 85.5% in EIF4E2 KO, and 33.2% in EIF4H KO cells compared to non-targeting control cells." (PMID 37803001, 2023). "The observation that the eif4e2 TILLING mutant (with a stop codon mutation in exon 1) is susceptible to potyviruses indicates that the knock-out of eIF4E2 is not sufficient to interfere with potyviral infection and therefore suggests a role for eIF4E2 that superimposes to the role of eIF4E1." (PMID 22242134, 2011). "Compared to non-targeting controls, ACE2, NFKBIA, EIF4E2, and EIF4H knockout cell lines showed a substantial decrease in infection." (PMID 37803001, 2023). "Notably, the protective phenotypes when targeting EIF4E2 and EIF4H do not appear to reflect a general effect of perturbing translation factors, as EIF4B did not significantly alter infection dynamics." (PMID 37803001, 2023).
degenerative disease (2 papers, 2022 to 2025). "GSEA assay showed that eIF4E2-GSK3β pathway was significantly associated with WNT signaling or neurodegenerative disease, both of which are highly related to GSK3β." (PMID 35568694, 2022).
of the lung (1 paper, 2017). "Finally, a detection method for disorders of the lung involving transcriptomic profiling was patented in 2005 that describes changes in EIF4E2 transcript levels (named eIF4EL3 in the patent) as a marker." (PMID 29317983, 2017).
EIF4E2 also shares sentences with these, for which no sentence is quoted: autism (1 paper); autism spectrum disorder (1); brain tumor (1); COVID-19 (1); depression (1); epilepsy (1); lung adenocarcinoma (1); memory impairment (1); neurodevelopmental disorder (1); uveal melanoma (1).